YIF1A (Yip1 interacting factor homolog A, membrane trafficking protein)
Description:
Possible role in transport between endoplasmic reticulum and Golgi.
Synonyms: 54TM; YIF1; YIF1P; FinGER7
Tractability: Antibody: UniProt predicts a signal peptide or a membrane-spanning region. PROTAC: ubiquitination databases record sites on it; its protein half-life has been measured.
Gene: Protein-coding gene on chromosome 11 (66,284,572 to 66,289,184, reverse strand). Ensembl gene ENSG00000174851.
Subcellular location: Endoplasmic reticulum membrane; Golgi apparatus membrane; Endoplasmic reticulum-Golgi intermediate compartment membrane
Subcellular location (Human Protein Atlas): Golgi apparatus; Vesicles
Pathways (Reactome):
Cellular responses to stimuli: XBP1(S) activates chaperone genes
Gene Ontology:
Molecular function: protein binding
Biological process: endoplasmic reticulum to Golgi vesicle-mediated transport
Cellular component: endoplasmic reticulum membrane; endoplasmic reticulum-Golgi intermediate compartment; endoplasmic reticulum-Golgi intermediate compartment membrane; Golgi apparatus; Golgi membrane; COPII-coated ER to Golgi transport vesicle
Genetic constraint (gnomAD): Loss-of-function variants: 28 observed, 32.37 expected, observed/expected ratio (o/e) 0.87, 90% interval 0.64 to 1.19. The upper end of that interval is the gene's LOEUF score, 1.19, which puts it in group 5 of 6, group 1 being the genes least tolerant of losing a copy. Missense variants: 373 observed, 405.05 expected, observed/expected ratio (o/e) 0.92, 90% interval 0.85 to 1. Synonymous variants: 175 observed, 169.66 expected, observed/expected ratio (o/e) 1.03, 90% interval 0.91 to 1.17.
Homologues: Orthologues: chimpanzee YIF1A (100% identical), macaque YIF1A (99% identical), pig YIF1A (97% identical), dog YIF1A (96% identical), mouse Yif1a (92% identical), rat Yif1a (91% identical), zebrafish yif1a (66% identical), Drosophila melanogaster Yif1 (40% identical), Caenorhabditis elegans yif-1 (39% identical). Paralogues in human: YIF1B (55% identical).
Diseases named in the same sentence as YIF1A in open-access papers:
YIF1A is named in the same sentence as 8 diseases in open-access papers, as found by Europe PMC text mining. Sharing a sentence is not in itself a finding about the gene and the disease. The quoted sentences say what the papers report.
amyotrophic lateral sclerosis type 8 (1 paper, 2019). Any amyotrophic lateral sclerosis in which the cause of the disease is a mutation in the VAPB gene. "YIPFβ1A/YIF1A was shown to interact with VAPB, a mutant of which (VAPB–P56S) has been linked to motor neuron degeneration in amyotrophic lateral sclerosis type 8 (ALS8)." (PMID 31417902, 2019).
epilepsy (1 paper, 2024). A brain disorder characterized by episodes of abnormally increased neuronal discharge resulting in transient episodes of sensory or motor neurological dysfunction, or psychic dysfunction. "The third complex subunit, Yif1p, has two human orthologues, YIF1A and YIF1B, andYIF1B mutations can also cause microcephaly and epilepsy, suggesting common pathomechanisms of the YIPF5,YIF1B and IER3IP1 disease-causing variants." (PMID 39115595, 2024).
squamous cell carcinoma (1 paper, 2019). A carcinoma arising from squamous epithelial cells. "Moreover, in samples from clinical squamous cell cancer, six genes (GAL, GSTP1, MRPL11, MRPL21, SF3B2, and YIF1A) at 11q13.1–13.3 and one gene (GALR1) at 18q23 showed significant differences in expression between normal and tumor samples." (PMID 31552180, 2019).
cancer (2 papers, 2015 to 2024). A tumor composed of atypical neoplastic, often pleomorphic cells that invade other tissues. "Despite the generally low PSI values for the 325 cryptic 3’SSs from the CLL-only analysis, we identified four genes previously implicated in cancer (TTI1, MAP3K7, FXYD5, PFDN5) and six others (YIF1A, ORAI2, ZNF91, ZNF548, RP11–1280I22." (PMID 25768983, 2015).
YIF1A also shares sentences with these, for which no sentence is quoted: bladder cancer (1 paper); microcephaly (1); neurodegenerative disease (1); tumor (1).